MFAP5 (microfibril associated protein 5)
Diseases named in the same sentence as MFAP5 in open-access papers (continued):
Sharing a sentence is not in itself a finding about the gene and the disease.
gastric cancer (2 papers, 2024). A primary or metastatic malignant neoplasm involving the stomach. "Overall, these findings suggested a potential mechanism that MFAP5 promoted gastric cancer progression through the MFAP5/Notch2/HEY1 signaling axis." (PMID 39524442, 2024). "Given the correlation between MFAP5 and ICI insensitivity, targeting MFAP5 could be a promising therapy to improve immunochemotherapy effects in gastric cancer by reshaping the desmoplastic and immunosuppressive microenvironment." (PMID 39524442, 2024). "BTG1 was reported to protect cells from oncogenic transformation; IGFBP7+ CAF was reported to promote gastric cancer; CAF-derived MFAP5 activated cell growth and migration in oral tongue squamous cell carcinoma via activation of MAPK and AKT pathways." (PMID 38686196, 2024).
head and neck squamous cell carcinoma (2 papers, 2020 to 2025). A squamous cell carcinoma that arises from any of the following anatomic sites: lip and oral cavity, nasal cavity, paranasal sinuses, pharynx, larynx, and salivary glands. "Microfibril-associated protein 5 is down-regulated in adipogenesis and up-regulated in head and neck squamous cell carcinoma during tumor replication." (PMID 41302034, 2025). "Our previous study has observed that overexpression of MFAP5 was correlated with lymph nodes metastasis and poor prognosis in head and neck squamous cell carcinoma (HNSCC), but the underlying mechanism is poorly understood." (PMID 32047565, 2020).
heart failure (2 papers, 2023). Inability of the heart to pump blood at an adequate rate to meet tissue metabolic requirements. "Remarkably, MFAP5 was found to be involved in the extracellular matrix remodeling of varicose veins and might serve as a biomarker for cardiac remodeling in heart failure, leading to the presumption that MFAP5 may also play a role in cardiovascular diseases." (PMID 37569268, 2023).
ischemia (2 papers, 2023 to 2025). A hypoperfusion of the BLOOD through an organ or tissue caused by a PATHOLOGIC CONSTRICTION or obstruction of its BLOOD VESSELS, or an absence of BLOOD CIRCULATION. "Comparable regional associations of MAP2, β3-tubulin, and MFAP5 were observed in the border zone on the ischemia-affected hemisphere." (PMID 40548074, 2025). "On the ischemia-affected hemisphere, the filament-like structures that are immunopositive for NF-L and MFAP5 at the same time became markedly visible in the border zone." (PMID 40548074, 2025). "This study thus aimed to explore local arrangements of MFAP5 with components of the neurovascular unit and extracellular matrix in non- and ischemia-affected neocortical brain regions of mice." (PMID 40548074, 2025). "Toward ischemia, the signals of NF-L and MFAP5 diminished and filaments appeared fragmented, whereas β-actin was diffusely maintained." (PMID 40548074, 2025). "For the first time, this study demonstrated ischemia-related alterations in tricellulin, MFAP5 and α-catenin along with the vasculature, extracellular matrix and cytoskeleton." (PMID 37569268, 2023). "In rats subjected to 4 h of focal cerebral ischemia, immunofluorescence labeling revealed comparable staining patterns of tricellulin, MFAP5 and α-catenin in the ischemia-affected neocortex for mice." (PMID 37569268, 2023). "For MFAP5, a gradual decrease in the immunosignal was observed along the ischemia-affected neocortex." (PMID 37569268, 2023). "Regarding MFAP5, a decreased immunosignal was observed in the ischemia-affected neocortex, accompanied by a decreased MAP2 signal and a slightly increased appearance of NF-L (E’)." (PMID 37569268, 2023). "However, the local arrangement of MFAP5 and its change due to ischemia was comparable to that of NF-L and MAP2." (PMID 40548074, 2025). "Consequently, MFAP5 is of interest for future studies addressing its functional properties in ischemia and the potential for neuroprotective approaches." (PMID 40548074, 2025). "Accompanied by the decreasing immunosignal of MFAP5 along the ischemia-affected neocortex, signals of MAP2 and NF-L decreased significantly (p-values ranging from 0.014 to 0.027), even though in this subset of analyses NF-L was found to decrease to a lesser degree." (PMID 37569268, 2023). "Along with an altered immunosignal of the cytoskeletal elements MAP2 and NF-L in the ischemia-affected neocortex, the present study revealed a gradually decreasing signal of tricellulin, MFAP5 and α-catenin toward the ischemic region of the neocortex, and also in the ischemic subcortex." (PMID 37569268, 2023). "Toward ischemia, filaments detected by MAP2 and MFAP5 appeared fragmented, and the immunosignal of β3-tubulin was found markedly diffused." (PMID 40548074, 2025). "The present study aimed to explore the local arrangement of MFAP5 with components of the NVU, ECM, and cytoskeleton in non- and ischemia-affected brain regions." (PMID 40548074, 2025). "Furthermore, these findings may extend the NVU perspective toward the involvement of closely associated extracellular matrix constituents in the setting of ischemia, which was shown for fibronectin in a previous investigation and for MFAP5 in the present study." (PMID 37569268, 2023). "Thereby, MFAP5 displayed similarities with MAP2 and NF-L concerning morphological characteristics in non-affected brain regions and exhibited comparable changes due to ischemia." (PMID 40548074, 2025).
keloid (2 papers, 2023 to 2025). An irregularly shaped, elevated mark on the skin caused by deposits of excessive amounts of collagen during wound healing. "MFAP5 was also expressed in keloids with primarily dermal and epidermal staining." (PMID 37253753, 2023). "Taken together, though, pathologic overexpression of MFAP5 in both fibroblasts and keratinocytes may contribute to keloid formation." (PMID 37253753, 2023). "MFAP5 was strongly expressed in keloids and was localized to both the dermis and epidermis." (PMID 37253753, 2023). "Our staining results in wound, keloid, and normal skin tissue coincide with previous work studying expression patterns of MFAP5 in various cancers and the predicted locations by Human Protein Atlas (proteinatlas.org), which also suggests that fibroblasts are a major source of MFAP515,19,22,33,53–56." (PMID 37253753, 2023). "Our prior work has also shown that MFAP5 is heavily expressed in the dermis and epidermis of keloids, which coincides with single‐cell RNA‐sequencing and partial transcriptomics studies demonstrating that keloid fibroblasts significantly overexpress MFAP5 as compared to NS fibroblasts." (PMID 41348119, 2025).
leiomyoma (2 papers, 2022). A well-circumscribed benign smooth muscle neoplasm characterized by the presence of spindle cells with cigar-shaped nuclei, interlacing fascicles, and a whorled pattern. "The feature selection resulted in a final model that consisted only of 19 genes, out of which only three, COL4A5, MFAP5, and ITGA9, were overexpressed in leiomyoma, while the rest were overexpressed in leiomyosarcoma)." (PMID 35216305, 2022).
lymph node metastasis (2 papers, 2019). "The univariate and multivariate analysis showed that MFAP5 protein level, tumor vascular invasion, lymph node metastasis, and tumor differentiation were prognostic factors for disease-free survival (DFS) and overall survival (OS)." (PMID 31775892, 2019). "Moreover, some researchers also found that there was a significant correlation between MFAP5 and lymph node metastasis, tumor metastasis and patient’s overall survival in early tongue cancer." (PMID 30899449, 2019). "We also found that overexpression of MFAP5 was significantly correlated with TNM staging and axillary lymph node metastasis in BLBC, suggesting that the MFAP5 gene plays an important role in the development and metastasis of BLBC." (PMID 30899449, 2019). "The upregulation MFAP5 in BLBC was related to TNM staging and axillary lymph node metastasis." (PMID 30899449, 2019). "MFAP5 level was significantly higher in ICC cases exhibiting positive lymph node metastasis (LNM) than in those without LNM (Sample numbers of Negative and Positive LNM were 156 and 52; P = 0.0189)." (PMID 31775892, 2019).
Obesity (2 papers, 2021 to 2023). Accumulation of substantial excess body fat. "For the second cis signal, clinical studies have linked MFAP5 levels with obesity-associated inflammation." (PMID 37778719, 2023).
Stroke (2 papers, 2023 to 2025). Sudden impairment of blood flow to a part of the brain due to occlusion or rupture of an artery to the brain. "This study comprehensively described MFAP5 after experimental stroke and identified similarities with MAP2 and NF-L." (PMID 40548074, 2025). "As circulating levels of NF-L and MAP2 were found to correlate with clinical and tissue-related outcomes in stroke patients, MFAP5 could also be applied as a serum marker that may help to tailor individual treatments." (PMID 40548074, 2025). "Further, MFAP5 might be considered as a target for neuroprotective approaches to preserve neuronal integrity and inhibit the transition toward long-term tissue damage due to stroke." (PMID 40548074, 2025). "Although these findings need to be confirmed by further studies, the present observations suggest that tricellulin, α-catenin and notably MFAP5 may play a role as cell-stabilizing elements in the brain and may thus represent a target for neuroprotective approaches in stroke." (PMID 37569268, 2023).
systemic sclerosis (2 papers, 2025). A chronic disorder, possibly autoimmune, marked by excessive production of collagen which results in hardening and thickening of body tissues. "Our identification of increased stromal microfibrillar-associated protein 5 (Mfap5, also known as MAGP-2) expression in TSK skin aligns with prior reports of elevated Mfap5 levels in the dermises of both TSK mice and patients with systemic sclerosis." (PMID 41008788, 2025). "Though we do not directly demonstrate a role for MFAP5 in fibrosis, studies have shown that MFAP5 expression is also in fibroblasts of fibrotic conditions such as idiopathic pulmonary fibrosis and systemic sclerosis‐associated skin and lung fibrosis." (PMID 41348119, 2025).
tongue cancer (2 papers, 2017 to 2019). A malignant neoplasm affecting the tongue. "This study also pointed out MFAP5 might be a mysterious target to predict the prognosis of cervical cancer and tongue cancer metastasis." (PMID 30899449, 2019).
breast tumors (1 paper, 2012). "Moreover, a few genes involved in modulation of the extracellular matrix (ADAMTS4, MMP1, MMP3, and angiogenesis (MFAP5, SFRP2, SRPK1, VEGF, and CHI3L1) were found to be expressed at higher levels in the primary breast tumors compared with the bone metastases." (PMID 23174366, 2012).
colorectal cancer (1 paper, 2023). A primary or metastatic malignant neoplasm that affects the colon or rectum. "Single-cell RNA sequencing, spatial transcriptomics, and bulk RNA sequencing datasets were integrated in this study to explore the biological properties of MFAP5 + fibroblasts and their interactions with tumor-infiltrating myeloid cells in colorectal cancer." (PMID 37344903, 2023).
esophageal cancer (1 paper, 2023). A primary or metastatic malignant neoplasm involving the esophagus. "Although UGT2B15 may influence the expression of COL5A1 and MFAP5, the functional role of these two genes in UGT2B15-induced esophageal cancer cell invasion and metastasis needs to be further clarified by rescue experimental validation." (PMID 38136265, 2023).
familial thoracic aortic aneurysms (1 paper, 2023). "Loss of function mutation of MFAP5 leads to familial thoracic aortic aneurysms and dissections, indicating a role in the ECM of vascular tissue." (PMID 38032942, 2023).
glioma (1 paper, 2021). A benign or malignant brain and spinal cord tumor that arises from glial cells (astrocytes, oligodendrocytes, ependymal cells). "High DEGs in grade II gliomas included NNMT, MFAP5, APCDD1L-AS1, C7orf57, HP, SERPINA5, and LTF and some highly downregulated DEGs included ABCA4, PDE6A, GRP, RD3, and TMEM72." (PMID 33948562, 2021).
lentivirus infection (1 paper, 2023). Virus diseases caused by the Lentivirus genus. "Then stable genetic knockdown (KD) of MFAP5 via lentivirus infection (CAF3_KD/ImdyCAF_KD) was performed and validated." (PMID 37156839, 2023).
Lymphatic Metastasis (1 paper, 2017). Transfer of a neoplasm from its primary site to lymph nodes or to distant parts of the body by way of the lymphatic system. "In conclusion, MFAP5 and TNNC1 could be potential markers for predicting occult cervical lymphatic metastasis and prognosis of oral tongue carcinoma." (PMID 27713166, 2017).
lymphedema (1 paper, 2025). Excess fluid collection in tissues, causing swelling. "Further expression analysis revealed that only four of these genes(POSTN, ASPN, FMOD, and MFAP5) exhibited statistically significant differential expression between lymphedema and control tissues, indicating their potential biological relevance in the fibrosis pathogenesis of lymphedema." (PMID 40881699, 2025).
metastasis (1 paper, 2017). The spread or migration of cancer cells from one part of the body (where they first appeared) to another. "Thus, TNNC1 appeared to be more sensitive than MFAP5 in predicting the prognosis of TSCC and its occult cervical lymphatic metastasis." (PMID 27713166, 2017).
non-small cell lung carcinoma (1 paper, 2024). A group of at least three distinct histological types of lung cancer, including non-small cell squamous cell carcinoma, adenocarcinoma, and large cell carcinoma. "For example, MFAP5 has been reported to enhance the stem cell features of non-small cell lung cancer cells, while the knockdown of MFAP5 has been shown to exert the opposite effect." (PMID 39759103, 2024).
oral cancers (1 paper, 2017). "However, the relationship between MFAP5 and TNNC1 in oral cancers remains unclear." (PMID 27713166, 2017).
osteoarthritis (1 paper, 2021). A noninflammatory degenerative joint disease occurring chiefly in older persons, characterized by degeneration of the articular cartilage, hypertrophy of bone at the margins and changes in the synovial membrane. "To explore the potential role played by MFAP5 in osteogenesis, we analyzed the GSE156508 database, which includes data on the primary osteoblasts of women with osteoporotic fractures (n = 6) and severe osteoarthritis (n = 6)." (PMID 34865619, 2021).
polyarticular JIA (1 paper, 2022). "CRLF1, MFAP5, and TNXB are overexpressed in persistent oligoarticular JIA FLS compared to polyarticular JIA FLS." (PMID 36167601, 2022).
renal fibrosis (1 paper, 2025). A final common manifestation of a wide variety of chronic kidney diseases characterized by glomerulosclerosis and tubulointerstitial fibrosis. "It is suggested that the concomitant upregulation of MFAP5 and CEACAM 5 and 6 is associated with renal fibrosis and cell transformation." (PMID 40699854, 2025).
serous ovarian cancer (1 paper, 2022). "Consistent with a role in tumor microenvironment, MFAP5 is present in cancer-associated fibroblasts of high-grade serous ovarian cancer and interacts with tumorigenic signaling." (PMID 35565312, 2022).
tongue squamous cell carcinoma (1 paper, 2023). A squamous cell carcinoma that arises from the tongue. "Microfibril-associated protein 5 (MFAP5) is highly expressed in CAFs of tongue squamous cell carcinoma and is associated with the activation of multiple pro-growth signaling pathways, such as MAPK signaling." (PMID 37143134, 2023).
tumor (48 papers, 2013 to 2025). "Mfap5 is also upregulated in cancer-associated fibroblasts across multiple solid tumors, reinforcing its role in fibrosis and tumor progression." (PMID 41008788, 2025). "Our study has elucidated the underlying pro-tumor mechanisms of tumor-resident MFAP5 + fibroblasts and provided valuable targets for the disruption of their properties." (PMID 37344903, 2023). "Studies have shown that microfibrillar-associated protein 5 (Mfap5), is a fibroblast derived factor, which can promote tumor cell epithelial-mesenchymal transition, migration and metastasis." (PMID 33828460, 2021). "Investigation of MFAP5 levels in patient tumours showed elevated levels in cancer-associated stroma." (PMID 32054041, 2020). "MFAP5 deficiency in CAFs could remodel the matrix via reducing HA secretion and inhibiting tumor cell proliferation simultaneously, in avoidance of disruption of matrix balance when merely eliminating HA." (PMID 37156839, 2023). "Hence, we hypothesized that abnormal crosstalk between MFAP5 + fibroblasts and other tumor-infiltrating immune cells could be an important cause of the aberrant biological behavior demonstrated by MFAP5 + fibroblasts in the CRC microenvironment." (PMID 37344903, 2023). "In cancer, enhanced tumor angiogenesis and micro‐vessel leakiness were attributed to activation of MFAP5 downstream of YAP or MFAP5‐induced expression of LPP." (PMID 41348119, 2025). "In normal tissues, there were few C1QC+ macrophages surrounding MFAP5+ fibroblasts, suggesting that crosstalk between these cell types occurred primarily within the tumor tissues." (PMID 40191203, 2025). "Herein, our TCGA database analysis revealed contrasting findings, showing underexpression of MFAP5 in EC tumor tissues, which differs from previous studies." (PMID 39759103, 2024). "Recently, most research studies indicated that MFAP5 expression is high in various tumor types, leading to enhanced tumor proliferation, endothelial cell motility, and angiogenesis." (PMID 39759103, 2024). "In particular, these highly expressed genes were notably associated with tumor development and metastatic progression, including A2M, AREG, chemokines (iCAFs-S1), BGN, MFAP5, THBS2, and TIMP1 (iCAFs-S2)." (PMID 39323622, 2024). "Our results revealed several tumor-specific signals between MFAP5 + fibroblasts and myeloid cells, particularly C1QC + macrophages." (PMID 37344903, 2023). "Our study highlights that tumor-associated fibroblasts (especially FAP + and MFAP5 + fibroblasts) can secrete MIF, which binds to the corresponding receptor CD74 on macrophages to drive immunological escape." (PMID 37344903, 2023). "We observed that the TME alters the biological behavior of tumor-resident MFAP5 + fibroblasts, conferring them with a pro-tumor tendency." (PMID 37344903, 2023). "The results showed that the tumour growth rates of the MFAP5 knockdown CAFs groups were significantly slower than that of the control (TRC) groups." (PMID 36855786, 2023). "In the MFAP5‐overexpressing CAFs group, the tumour growth rate was markedly higher than that in the control (Vector) group." (PMID 36855786, 2023). "Apart from these findings, clinicopathological analysis of the in-house serum samples showed that high-level serous MFAP5 was associated with higher CEA level and poorer tumor differentiation of PDAC patients." (PMID 37156839, 2023). "The results demonstrated that MFAP5 was upregulated in almost all normal tissues of diverse tumor types, particularly in COAD and READ." (PMID 37344903, 2023). "Our findings again suggested the higher expression of MFAP5 in normal tissues as compared with that in tumor sites." (PMID 37344903, 2023). "In these cancers, MFAP5 alters cellular phenotype in various cell types in the tumor microenvironment to promote fibrosis, angiogenesis, and chemoresistance." (PMID 37253753, 2023).